ASPG (asparaginase)
Diseases named in the same sentence as ASPG in open-access papers (continued):
Sharing a sentence is not in itself a finding about the gene and the disease.
acute lymphoblastic leukemia (continued). "Currently, native L-ASNase from Escherichia coli (EcA) or Dickeya dadantii (formerly known as Erwinia chrysanthemi) (ErA), along with the pegylated form of E. coli asparaginase, are successfully used for the treatment of patients with acute lymphoblastic leukemia." (PMID 35335974, 2022). "The bacterial enzyme asparaginase is the main treatment option for acute lymphoblastic leukemia." (PMID 34681778, 2021). "Additionally, patients with acute lymphoblastic leukemia (ALL) typically receive asparaginase treatment to lower asparagine levels in order to block the growth and survival of cancer cells." (PMID 33916846, 2021). "Asparaginase, a component of a multi-agent chemotherapeutic regimen for treatment of pediatric and adult patients with acute lymphoblastic leukemia (ALL), converts asparagine and glutamine to aspartate and glutamate, respectively, decreasing plasma concentrations of asparagine and glutamine." (PMID 33199836, 2021). "Thus, asparaginase, which functions by depletion of asparagine and glutamine, is a first line of treatment for B-Cell-derived acute lymphoblastic leukemia (B-ALL)." (PMID 30364637, 2018). "Thus asparaginase is developed as one of the most important chemotherapeutic agents against pediatric acute lymphoblastic leukemia." (PMID 27157636, 2016). "Bacterial asparaginase (L-Asparaginase amidohydrolase, E.C. 3.5.1.1) is a selective and highly effective chemotherapeutic agent extensively used in first-line treatment of acute lymphoblastic leukemia (ALL), acute myeloblastic leukemia (AML) and other tumor malignancies in human." (PMID 26891220, 2016). "A vital treatment for acute lymphoblastic leukemia (ALL) is also asparaginase, an enzyme that degrades the amino acid asparagine." (PMID 40300030, 2025). "Pegaspargase is a pegylated formulation of E. coli-derived asparaginase, which when combined with multi-agent chemotherapy is an effective, well-established therapy for acute lymphoblastic leukemia (ALL)." (PMID 40163215, 2025). "Although asparaginase, a drug that depletes serum asparagine, has been successfully applied in the clinical treatment of acute lymphoblastic leukemia (ALL), its efficacy in solid tumors such as gastric cancer is limited." (PMID 41229436, 2025). "Consistent with this approach, depleting asparagine levels using asparaginase is a clinically established treatment for Acute Lymphoblastic Leukemia (ALL)." (PMID 40867591, 2025). "Asparaginase is a therapeutic enzyme widely used in the treatment of acute lymphoblastic leukemia (ALL) by depleting plasma asparagine." (PMID 40535116, 2025). "FDA approval for PEGylated asparaginase (Rhone-Poulenc Rorer as Oncaspar®) was granted in 1994 for the treatment of acute lymphoblastic leukemia (ALL) patients who are hypersensitive to the two native isoforms of the enzyme." (PMID 38523641, 2024). "Hence, novel ideas, such as transfusing asparaginase-loaded RBCs in patients with acute lymphoblastic leukemia, could possibly be extended to additional disorders." (PMID 38270470, 2024). "The key component of treating B-cell acute lymphoblastic leukemia (B-ALL) is pegylated (PEG)-asparaginase with glucocorticoids and other chemotherapeutic agents." (PMID 39011188, 2024). "A cross‐sectional nationwide study was designed to assess national compliance with international consensus/guidelines of monitoring asparaginase levels in children with acute lymphoblastic leukemia (ALL) treated with asparaginase in routine clinical practice." (PMID 36307379, 2023). "Interestingly, in one instance, the significance of Asn for cancer cell proliferation was initially identified by the anti-cancer efficacy of extracellular asparaginase treatment of childhood acute lymphoblastic leukemia (ALL), which typically expresses low levels of ASNS." (PMID 37111157, 2023).
acute lymphoblastic leukemia (continued). "The enzyme asparaginase, which changes the amino acid asparagine into aspartic acid and ammonia, is a crucial part of acute lymphoblastic leukemia (ALL) therapy." (PMID 36670946, 2022). "A very recent study also demonstrated synergy between eprenetapopt and asparaginase (an enzyme that degrades asparagine) in acute lymphoblastic leukemia cell lines, which could hint that GSH depletion by eprenetapopt more generally increases cancer cell dependency on exogenous amino acid uptake." (PMID 36103522, 2022). "In acute lymphoblastic leukemia (ALL) isolated HF has most commonly been attributed to asparaginase (ASP) delivery." (PMID 35407383, 2022). "Asparaginase (ASNase) is a widely applied chemotherapeutic drug that is used to treat Acute Lymphoblastic Leukemia (ALL); however, immune responses and silent inactivation of the drug often limit its bioavailability." (PMID 34834379, 2021). "Furthermore, A6E mutation could be introduced to the ASNS gene of acute lymphoblastic leukemia patients to inhibit the upregulation of ASNS by cancer cells, reducing the risk of developing resistance to the asparaginase treatment." (PMID 33916846, 2021). "Asparaginase is one of the essential chemotherapies used to treat acute lymphoblastic leukemia (ALL)." (PMID 34711008, 2021). "Clinical trials of native asparaginase in patients with acute lymphoblastic leukemia (ALL) have shown high immunogenicity, hepatotoxicity, and toxicity to the pancreas." (PMID 34832852, 2021). "Asparaginase is a basic component of chemotherapy in pediatric acute lymphoblastic leukemia (ALL) and has played a crucial role in improving the long-term survival of this disease." (PMID 34640436, 2021). "For the past four decades, asparaginase (ASNase) has been an important therapeutic agent for acute lymphoblastic leukemia (ALL)." (PMID 34267184, 2021). "In another case, PEG-asparaginase was generated and commercialized as Oncaspar for the treatment of acute lymphoblastic leukemia (ALL)." (PMID 32024289, 2020). "Asparaginase, an injectable enzymatic drug that degrades asparagine in the plasma, is a “cornerstone” of treatment for acute lymphoblastic leukemia (ALL)." (PMID 31096630, 2019). "Asparagine depletion via asparaginase in acute lymphoblastic leukemia (ALL) is an example for interference with amino acid availability as clinically established anti-tumor strategy." (PMID 31824848, 2019). "Erwinia asparaginase, a bacteria-derived enzyme drug, has been used in the treatment of various cancers, especially acute lymphoblastic leukemia (ALL)." (PMID 28358370, 2017). "The inclusion of asparaginase in chemotherapy regimens to treat acute lymphoblastic leukemia (ALL) has had a positive impact on survival in pediatric patients." (PMID 26421220, 2015). "Asparaginase is widely used in chemotherapeutic regimens for the treatment of acute lymphoblastic leukemia (ALL) and has led to a substantial improvement in cure rates, especially in children." (PMID 25586605, 2015). "Asparaginase (ASNase) is a component of highly effective chemotherapeutic regimens used to treat pediatric acute lymphoblastic leukemia (ALL) and some lymphomas." (PMID 26178806, 2015). "Cellular asparagine reliance has been exploited successfully in the treatment of acute lymphoblastic leukemia (ALL) with bacterially derived asparaginase." (PMID 26499495, 2015). "Transient hyperglycemia (TH) is a recognized side effect of the corticosteroids and asparaginase given during induction chemotherapy for pediatric acute lymphoblastic leukemia (ALL)." (PMID 24734157, 2014). "Asparaginase is a chemotherapeutic agent used to induce disease remission in children with acute lymphoblastic leukemia (ALL)." (PMID 25405049, 2014). "Asparaginase is a chemotherapeutic agent used in most remission induction protocols for children with acute lymphoblastic leukemia (ALL)." (PMID 25405049, 2014). "Asparaginase is essential for treating T‐cell acute lymphoblastic leukemia (T‐ALL)." (PMID 38888368, 2024).
acute lymphoblastic leukemia (continued). "Some cancers, such as acute lymphoblastic leukemia (ALL), depend on asparagine availability to maintain cell survival, which is exploited clinically with the use of the bacterially derived enzyme asparaginase that depletes asparagine." (PMID 37686063, 2023). "For the treatment of acute lymphoblastic leukaemia (ALL) and malignant lymphoma patients, asparaginase is an important agent." (PMID 37839090, 2023). "Since then, several asparaginase preparations have been FDA (Food and Drug Administration) approved for treatment of pediatric and adult hematological malignancies, particularly acute lymphoblastic leukemia." (PMID 37601686, 2023). "Acute lymphoblastic leukemia (ALL) barely expresses ASNS and is thus sensitive to asparagine depletion therapy by asparaginase (ASNase)." (PMID 36284275, 2022). "Asparaginase was the first Food and Drug Administration (FDA)-approved amino acid degrading enzyme used to treat acute lymphoblastic leukemia (ALL)." (PMID 36358940, 2022). "Glutamine synthetase (GLUL), is of major interest, because this enzyme may be a resistance factor in metabolic cancer treatments; like the asparaginase treatment for acute lymphoblastic leukemia (ALL) and solid cancer." (PMID 36032676, 2022). "Asparaginase (ASNase) is a biopharmaceutical for Acute Lymphoblastic Leukemia (ALL) treatment." (PMID 33922106, 2021). "Asparaginase plays an integral role in chemotherapy for acute lymphoblastic leukemia (ALL)." (PMID 34513489, 2021). "A similar therapy in acute lymphoblastic leukemia (ALL) to limit the access to asparagine (essential amino acid for certain ALL blasts) using asparaginase, was the first successful metabolism-based therapy, which was introduced some decades ago and is still used in ALL treatment." (PMID 32993063, 2020). "Human highly metastasis lung cancer cell line 95D, which showed drug resistance to asparaginase, served as ASNS-positive control and human acute lymphocytic leukemia cell line Jurkat served as ASNS-negative control." (PMID 29207624, 2017). "Asparaginase, an enzyme drug which deprives tumor cells of semi-essential L-asparagine by hydrolyzing extracellular L-asparagine into L-aspartic acid and ammonia, has been used clinically for treating acute lymphoblastic leukemia (ALL) since early 1970s." (PMID 29207624, 2017). "ASN Asparagine (Asn) depletion by means of the bacterial enzyme asparaginase (ASNase) is presently the only approved anticancer treatment based on an AA-depleting approach and has been long used as an anticancer strategy, especially toward pediatric acute lymphoblastic leukemia (ALL)." (PMID 36428783, 2022). "In the 1970s, asparaginase (ASNase), an enzyme extracted from Escherichia coli (E. coli) was found to decrease Asn levels by catalyzing the hydrolysis of Asn, leading to the clinical application of L-asparaginase as an anti-cancer therapy for acute lymphoblastic leukemia (ALL) patients." (PMID 36090030, 2022). "Polyethylene glycol-conjugated asparaginase (PEG-ASP) has a lower immunogenicity and longer circulating half-life than unconjugated L-ASP, and has been reported to be effective and well-tolerated in children with acute lymphoblastic leukemia." (PMID 30241515, 2018). "Asparaginase, a recombinant bacterial enzyme that converts asparagine to aspartate and ammonia, reducing the plasma levels of the first, has been approved by FDA for the treatment of childhood acute lymphoblastic leukemia." (PMID 29805774, 2018). "Asparaginase products, which are approved for treatment of acute lymphoblastic leukemia (ALL), but not AML, do not suppress the bone marrow and can provide a treatment option for patients with AML who do not wish to receive blood transfusion." (PMID 27064021, 2016). "For example, Oncaspar®, a pegylated form of the enzyme asparaginase (PEG-ASNase), was approved by the FDA in 1994 for pediatric Acute Lymphoblastic Leukemia (ALL)." (PMID 37896191, 2023).
acute lymphoblastic leukemia (continued). "Asparaginase, which is also listed on WHO list of essential medicines, is a drug used to treat acute lymphoblastic leukemia (ALL), acute myeloid leukemia (AML), and non-Hodgkin’s lymphoma, and was discovered more or less by coincidence." (PMID 30893889, 2019). "In a multicenter, prospective Prophylactic Antithrombin Replacement in Kids with Acute Lymphoblastic Leukemia Treated with Asparaginase (PARKAA) study, 8 of 60 (13%) children with ALL had APLA; four of them developed CVL related TE." (PMID 28472942, 2017). "Native asparaginase from E. coli and Erwinia chrysanthemi was approved by the US Food and Drug Administration (FDA) in 1994 and 2011, respectively, for use in patients with acute lymphoblastic leukemia (ALL)." (PMID 37762044, 2023). "For instance, in acute lymphoblastic leukemia (ALL), in which low ASNS expression was found, further depletion of asparagine achieved by the introduction of asparaginase (hydrolyzing asparagine to aspartic acid and ammonia) was shown to be lethal in ALL cells and used as a treatment strategy." (PMID 35158820, 2022). "HAM-A is unique in that it incorporates short-acting asparaginase, a drug normally used for acute lymphoblastic leukemia (ALL) rather than AML." (PMID 32079074, 2020). "Pegylated‐asparaginase (PEG‐asparaginase), a long‐acting formulation of L‐asparaginase, is used as a treatment for Philadelphia‐negative acute lymphoblastic leukemia (ALL)." (PMID 36819167, 2023).
leukemia (66 papers, 2013 to 2026). A malignant (clonal) hematologic disorder, involving hematopoietic stem cells and characterized by the presence of primitive or atypical myeloid or lymphoid cells in the bone marrow and the blood. "To validate that loss of SOD2 sensitizes leukemia cells to asparaginase, we first induced an shorth hairpin RNA (shRNA)-mediated knockdown of SOD2 (shSOD2), which resulted in efficient gene silencing as assessed by RT-qPCR and western blot." (PMID 40131931, 2025). "Individual susceptibility to asparaginase therapy has potential to inform its utilisation across the subtypes of leukaemia on a case-by-case basis, perhaps changing the outlook on asparaginase as an increasingly targeted therapy for both ALL and AML." (PMID 39766036, 2024). "Frequently, AAP leads to truncation of asparaginase therapy, which can increase the risk of leukemia relapse, making the reintroduction of asparaginase a critical consideration." (PMID 39564382, 2024). "This investigation sought to delineate the causal nexus between plasma glutamine concentrations and leukemia susceptibility utilizing bidirectional Mendelian Randomization (MR) analysis and to elucidate the metabolic ramifications of asparaginase therapy on glutamine dynamics in leukemia patients." (PMID 39050845, 2024). "Moreover, asparaginase therapy can cause hypersensitivity reactions and development of asparaginase-antibodies that limit the action of the drug and increase the risk of leukemia relapse." (PMID 35237305, 2022). "Similarly, in B-cell ALL IGFBP7 expression in BMSCs was found to be associated with asparaginase resistance and decreased leukemia-free survival." (PMID 25887188, 2015). "Of note, inhibition of SOD2 or UBRs highly sensitized drug-resistant human leukemia PDXs to asparaginase." (PMID 40131931, 2025). "Pediatric treatments include multiple doses of asparaginase, more frequent use of vincristine and steroids and intensive prevention of leukaemia in the central nervous system, along with a longer maintenance phase." (PMID 41333359, 2025). "Asparaginase (ASPG) is an approved drug that breaks down circulating asparagine in leukemia cells, thereby depriving cancer cells of asparagine and inhibiting cancer growth." (PMID 40808257, 2025). "Red blood cells have been employed to encapsulate enzymes like asparaginase for leukemia therapy, extending enzyme half-life and reducing immunogenicity." (PMID 40871101, 2025). "Our research ventured into analyzing plasma glutamine levels across distinct groups, including healthy subjects, leukemia patients before chemotherapy, and leukemia patients after treatment with asparaginase." (PMID 39050845, 2024). "Our study underscores the crucial role of glutamine metabolism in the context of leukemia and its treatment, particularly highlighting the significant impact of asparaginase therapy on plasma glutamine levels." (PMID 39050845, 2024). "Asparaginase is known as an anti-cancer agent that is effective for the treatment of certain lymphomas and leukemias by growth inhibition of human cancer cells." (PMID 39315287, 2024). "The paper presents the concept of developing a combined anti-leukemia treatment that combines two components: asparaginase (ASP) and doxorubicin (Dox)." (PMID 39125158, 2024). "Asparaginase, a chemotherapy drug often used in some leukemia treatments, primarily targets asparagine, depleting its levels in the blood and corresponding tumor microenvironment." (PMID 39050845, 2024). "It has been shown that pharmacological inhibition of GSK3 profoundly sensitizes drug-resistant leukemias to asparaginase." (PMID 38539506, 2024). "Accordingly, asparaginase re-exposure should be determined mainly based on the anticipated requirement for asparaginase to achieve effective anti-leukaemia results." (PMID 39439952, 2024).